PTH (parathyroid hormone)
Diseases named in the same sentence as PTH in open-access papers (continued):
Sharing a sentence is not in itself a finding about the gene and the disease.
Hypercalcemia (continued). "During clinical and laboratory monitoring at the age of 13, hypercalcemia (1.57 nmol/l), hypophosphatemia (3.7 mg/dl), calciuria 34.5 mg/dl (RV 6–21 mg/dl) were identified asymptomatically, and parathyroid hormone (PTH) dosed at 91.3pg/ml (RV 10–68 pg/ml)." (PMID 40136120, 2025). "They used synthetic human and bovine PTH peptides to trigger the generation of antibodies in a patient with parathyroid carcinoma and metastases, severe bone disease, extreme hypercalcemia, and resistance to conventional treatment." (PMID 40177730, 2025). "Biochemical investigations demonstrated persistent hypercalcemia, elevated parathyroid hormone, and significantly raised fasting gastrin levels whilst off high-dose PPI, raising suspicion for MEN1 syndrome." (PMID 41541958, 2025). "Another exceptional case of a GPA mimicking PC and measuring 6.5 cm with milder preoperative hypercalcemia of 12.5 mg/dl and PTH of 2.747 pg/ml was published in 2020." (PMID 39831932, 2025). "In our patient, the ingestion of 20,000 IU of vitamin D daily led to hypercalcaemia with subsequent parathyroid hormone suppression." (PMID 41362524, 2025). "One of the endocrine conditions that endocrinologists see the most frequently is primary hyperparathyroidism, which is brought on by a parathyroid adenoma secreting excessive levels of parathyroid hormone (PTH) and consequently hypercalcaemia." (PMID 40119143, 2025). "Hypercalcaemia with suppressed parathyroid hormone and hypercalciuria are hallmarks of such toxicity, as seen in our patient." (PMID 41362524, 2025). "Following parathyroidectomy, his hypercalcemia resolved, and his PTH level decreased to 87.8 pg/mL one-month post-surgery, although it did not fully normalize." (PMID 40451790, 2025). "The youngest sibling had a more distinctive pattern, with episodes of hypercalcaemia accompanied by normal parathyroid hormone and vitamin D levels, together with sporadic proteinuria and phosphaturia." (PMID 41465172, 2025). "Primary hyperparathyroidism is characterized by elevated levels of parathyroid hormone (PTH) leading to hypercalcemia and hypophosphatemia." (PMID 40342445, 2025). "The labs demonstrate persistent hypercalcaemia and elevated parathyroid hormone (PTH) preoperatively, with normalization of both parameters following surgery." (PMID 41523514, 2025). "Given PTH-independent hypercalcemia with inappropriately elevated 1,25-OH vitamin D, a malignancy workup was pursued." (PMID 41024908, 2025). "Serum calcium levels also influence the use of specific therapies to address other laboratory levels such as serum PTH and phosphate, such that hypercalcemia favors the use of calcimimetics while hypocalcemia favors vitamin D therapies for PTH lowering (100%)." (PMID 39888902, 2025). "Given the suppressed intact PTH, elevated serum calcium, and a large GIST, malignancy-associated hypercalcemia was strongly suspected." (PMID 41479802, 2025). "Primary hyperparathyroidism (PHPT) is a relatively well-recognised endocrine disorder among clinicians, particularly due to its characteristic laboratory findings such as hypercalcaemia and elevated parathyroid hormone (PTH) levels." (PMID 41368866, 2025). "Hypercalcemia with an elevated or inappropriately elevated PTH level is indicative of PTH-dependent hypercalcemia." (PMID 41479802, 2025). "Some of these emerging therapies include calcimimetics such as cinacalcet, which help regulate PTH production and manage hypercalcemia, and PTHrP inhibitors, aimed at blocking the peptide involved in tumor growth and metastasis." (PMID 40177427, 2025). "Most patients with PC present with severe hypercalcemia (65–75%), generally above 14 mg/dl or 3–4 mg/dl above the upper limit of normal, while PTH levels are usually 5 to 10 times higher than normal." (PMID 39831932, 2025). "Blood tests revealed that she had hypercalcemia, high serum bilirubin, and high serum parathyroid hormone." (PMID 38406045, 2024).
Hypercalcemia (continued). "Accumulation of these active forms of vitamin D3 enhances intestinal Ca absorption and bone reabsorption, resulting in hypercalcemia, hypercalciuria, nephrocalcinosis, and suppressed intact parathyroid hormone." (PMID 38504242, 2024). "It results in unopposed PTH activity that leads to skeletal demineralization, decreased renal calcium excretion, and persistent hypercalcemia." (PMID 39129820, 2024). "After all, our findings demonstrated increased renal stiffness which is related to hypercalcemia and elevated PTH levels in patients with aPHPT." (PMID 38280162, 2024). "Before the reoperation (VATS thymectomy), laboratory findings showed elevated PTH (1,171 ng/L; reference range: 21.80 ng/L–87.5 ng/L) and hypercalcemia (13.4 mg/dL; reference range: 8.4 mg/dL–10.2 mg/dL)." (PMID 39444450, 2024). "Approximately 90% of PCs are functional, meaning that they produce excessive PTH which leads to hypercalcemia." (PMID 39768933, 2024). "The anamnesis revealed incidental detection of hypercalcemia and elevated PTH levels during her previous hospitalization with grade 3 splenic laceration after intra-vehicle traffic accident (on July 2023)." (PMID 39444450, 2024). "Primary hyperparathyroidism (PHPT) is a common endocrine disorder characterized by hypercalcemia and elevated parathyroid hormone levels." (PMID 38957316, 2024). "CasrBCH002 mice recapitulate several features of FHH1 including hypercalcemia, an inappropriately normal PTH which is higher than expected for the degree of hypercalcemia." (PMID 38386045, 2024). "This case demonstrates an atypical presentation of PJP infection in a chronically immunosuppressed patient on rituximab, presenting with PTH-independent hypercalcemia." (PMID 38658913, 2024). "PC should be suspected in patients with marked hypercalcemia (>14 mg/dL) and parathyroid hormone (PTH) levels 10 times or more than the upper limit." (PMID 39768933, 2024). "For patients diagnosed with SHPT, invasive treatments are recommended if they exhibit symptoms or meet criteria such as persistent elevation in serum PTH levels, hypercalcaemia or hyperphosphataemia with inadequate medication response." (PMID 39208984, 2024). "In this case, despite PTH levels being suppressed, we decided against the latter as an alternative explanation for ‘hypercalcaemia with suppressed PTH’ in the form of hyperthyroidism was evident." (PMID 39434928, 2024). "Steroids, particularly in high doses during the initial post-transplant period, can lead to hypercalcemia by inducing enzymes involved in vitamin D metabolism, which increases both parathyroid hormone and fibroblast growth factor 23 levels." (PMID 39064308, 2024). "We found that with the elevated PTHrP, normal PTH, and normal vitamin D levels, hypercalcemia of malignancy was highly likely." (PMID 39449942, 2024). "This case presentation aims to describe swallowing difficulty as a potential primary symptom of parathyroid hormone (PTH)-mediated hypercalcemia." (PMID 39427404, 2024). "PHPT is a disease characterized by the excessive secretion of parathyroid hormone, leading to hypercalcemia, osteoporosis, and urinary tract stones." (PMID 38957316, 2024). "The pathophysiology of hypercalcemia in lymphomas is often related to the secretion of parathyroid hormone (PTH)-related peptide (PTHrP)." (PMID 39677199, 2024). "We presented a rare case of PTH-rp production in a giant myoma, inducing hypercalcemia in pregnancy." (PMID 39148641, 2024). "The quantity and activity of these receptors decrease, and as a result, there is a pathological enlargement of the parathyroid gland, decreased cellular sensitivity to hypercalcemia, and excessive secretion of parathyroid hormone (PTH)." (PMID 39519190, 2024). "Familial hypocalciuric hypercalcemia (FHH) is a rare, benign genetic disorder that typically presents with mild to moderate hypercalcemia, low urinary calcium excretion, and normal to slightly elevated levels of parathyroid hormone (PTH)." (PMID 39246902, 2024).
Hypercalcemia (continued). "Familial hypocalciuric hypercalcemia type I (FHH1, OMIM: #145980) is a genetic disorder characterized by hypercalcemia, hypocalciuria, normal to mildly elevated PTH levels, and in some patients mildly reduced bone mineral density and hypermagnesemia." (PMID 38386045, 2024). "This case report describes a remarkable improvement in bone mineral density (BMD) in a 95-year-old female with parathyroid hormone (PTH)-mediated hypercalcemia following treatment with zoledronic acid." (PMID 39669861, 2024). "Nine out of 11 patients had a normal calcium load test and 2 had postload hypercalcemia (postload PTH <30 pg/mL in 1)." (PMID 38497124, 2024). "In conclusion, vitamin D toxicity is an important differential diagnosis in patients with PTH-independent hypercalcemia and can be refractory to standard therapy." (PMID 39337491, 2024). "PTH-related hypercalcemia is often due to primary hyperparathyroidism, while non-PTH-related hypercalcemia can result from malignancies, granulomatous diseases, endocrine disorders, or vitamin D intoxication." (PMID 39559636, 2024). "Of note, in 2021, an exceptional case of pancreatitis synchronously presenting both mechanisms of hypercalcemia (PTH-dependent and -independent) was reported." (PMID 38928056, 2024). "The diagnosis of PTH-mediated hypercalcemia was made based on comprehensive lab findings prior to the administration of zoledronic acid." (PMID 39669861, 2024). "Eight (8.79%) subjects had vitamin D toxicity-related hypercalcaemia; all of these subjects had suppressed PTH." (PMID 39526047, 2024). "The constellation of hypercalcemia, elevated PTH levels, hypophosphatemia, and the difficulty in localizing the parathyroid adenoma within the neck strongly suggested an ectopic parathyroid tumor." (PMID 39371798, 2024). "A retrospective analysis of advanced thyroid cancer patients also showed that MTKIs reduce calcium levels through both PTH-dependent and PTH-independent mechanisms, suggesting their efficacy in correcting hypercalcemia in PC." (PMID 39056047, 2024). "Two years later, biochemical tests showed recurrence of hypercalcaemia with suppressed parathyroid hormone levels and elevated 1,25(OH)2D3 concentrations." (PMID 38665259, 2024). "Upon examination, mild hypercalcemia and elevated levels of parathyroid hormone (PTH) were observed." (PMID 38363524, 2024). "Of the 42 subjects with PTH-dependent hypercalcaemia, 38 subjects were diagnosed with solitary parathyroid adenoma on sestamibi scan and neck USG." (PMID 39526047, 2024). "Hypercalcemia due to sarcoidosis typically presents with low PTH levels, low 25-hydroxyvitamin D levels, and elevated 1,25-dihydroxyvitamin D levels, which were all seen in our patient." (PMID 39051296, 2024). "This case report describes a patient presenting with symptomatic hypercalcaemia with suppressed PTH, in whom the simultaneous workup showed the presence of hyperthyroidism, leading to an eventual diagnosis of autoimmune hyperthyroidism-mediated hypercalcaemia." (PMID 39434928, 2024). "Tertiary hyperparathyroidism is characterized by an exaggerated secretion of PTH due to prolonged secondary hyperparathyroidism, leading to the development of hypercalcemia." (PMID 39463573, 2024). "Major signs of FHH1 include hypercalcemia, hypocalciuria, normal to elevated PTH, and variably hypophosphatemia, hypermagnesemia, and mild bone mineralization defects." (PMID 38386045, 2024). "We present the case of a middle-aged female with hypercalcaemia with reduced PTH levels despite vitamin insufficiency, who was eventually diagnosed with autoimmune hyperthyroidism." (PMID 39434928, 2024). "KT recipients with no treatment had shorter dialysis vintage (P = .017) and lower PTH at KT (P = .002), later onset of hypercalcemia post-KT (P < .001)." (PMID 38006197, 2024).
Hypercalcemia (continued). "Drug induced hypercalcemia is commonly related to the use of thiazide diuretics or lithium, in less frequent cases also to vitamin A supplements or recombinant human parathyroid hormone (rhPTH)." (PMID 39529981, 2024). "Most of these patients, in addition to hypercalcaemia with suppressed PTH, would have classical hyperthyroidism symptoms including palpitation, shakiness, irritable mood and weight loss." (PMID 39434928, 2024). "Artificial suppression of PTH was particularly likely if a PTH level below the normal range and simultaneous hypercalcemia were detected (5 patients during “F2” visit)." (PMID 39636417, 2024). "This case highlights an atypical presentation of PTH-mediated hypercalcemia where dysphagia was the primary symptom." (PMID 39427404, 2024). "HPT with hypercalcemia is frequent at time of KT with normalization of PTH and calcium in a substantial proportion of patients after a KT." (PMID 39001249, 2024). "Several findings suggest that part of the phenotype is independent from PTH, namely hypercalcemia, and higher FGF23 (both intact and C-terminal fragment)." (PMID 38386045, 2024). "While low and short-term dosing of intermittent PTH is osteoanabolic, high dosing stimulates bone resorption and induces hypercalcemia." (PMID 38706880, 2024). "Concurrently, the PTH level of 19.4 pg/mL, while within the low-normal range, was not adequately suppressed as would be expected in cases of non-PTH-mediated hypercalcemia." (PMID 39669861, 2024). "Primary hyperparathyroidism (PHPT) usually presents with symptoms of hypercalcemia which is due to excessive secretion of parathyroid hormone (PTH)." (PMID 38650780, 2024). "Primary hyperparathyroidism (PHPT) is a common endocrine disease characterized by hypercalcemia and high or inappropriately normal levels of parathyroid hormone (PTH)." (PMID 38474319, 2024). "Primary hyperparathyroidism (PHPT) is a condition characterized by hypercalcemia resulting from the excessive, uncontrolled secretion of parathyroid hormone (PTH)." (PMID 39822449, 2024). "We present a case of a 75-year-old woman with persistent hypercalcemia (serum calcium 10.7 mg/dL, ionized calcium 1.37 mmol/L), elevated parathyroid hormone levels (86.6 pg/mL), and significantly low 24-hour urinary calcium excretion (<11 mg/24 hours)." (PMID 39246902, 2024). "At the time of hospitalization, laboratory tests revealed severe hypercalcemia (5.37 mmol/L; normal range: 2.0-2.7 mmol/L) and a significantly increased serum PTH level (613.3 pg/mL; normal range: 12-88 pg/mL)." (PMID 39777339, 2024). "In humans, mutations in the CaSR cause familial hypocalciuric hypercalcemia in heterozygotes and neonatal severe hyperparathyroidism in homozygotes, resulting in inappropriately normal or elevated PTH concentrations in the face of hypercalcemia." (PMID 38887540, 2024). "In PTH-independent hypercalcaemia, the PTH level is appropriately suppressed for hypercalcaemia status." (PMID 38665259, 2024). "When accounting for reference range changes in pregnancy, investigation into the etiology of hypercalcemia revealed suppressed parathyroid hormone (PTH), normal 25-OH vitamin D, and elevated thyroid hormones." (PMID 38784190, 2024). "In cases of hypercalcaemia with suppressed PTH, clinicians often consider malignancy, granulomatous disorders, drugs and other systemic conditions." (PMID 39434928, 2024). "These individuals present with hypercalcemia, hypercalciuria, kidney stones, and suppressed levels of PTH." (PMID 38676447, 2024). "Although primary on the second admission, PTH was adequately suppressed for the level of hypercalcemia, ruling out this disease." (PMID 39350812, 2024). "The typical complications of long standing hypercalcemia and increased PTH were reported:, for instance, premenopausal osteoporosis in young females and a middle- aged male with a low bone mineral density." (PMID 38396977, 2024).
Hypercalcemia (continued). "FHH-positive patients had more frequently a positive family history, a lower prevalence of kidney stones, lower serum PTH levels, higher serum Mg2+ levels and were less often treated for hypercalcemia." (PMID 38214877, 2024). "PHPT is characterized by hypercalcemia, with either raised or normal (~ 80%) parathyroid hormone (PTH) concentrations." (PMID 38038882, 2024). "We describe the first case to our knowledge of severe, symptomatic hypercalcemia found to be secondary to a PTH-secreting pancreatoblastoma." (PMID 39611185, 2024). "Posttreatment imaging should be performed when there is a suspicion of recurrence or elevated PTH or hypercalcemia." (PMID 39061231, 2024). "Hypercalcaemia with suppressed parathyroid hormone (PTH) typically raises concern for malignancy-related, granulomatous disorder-related or drug-related hypercalcaemia but can occasionally be caused by less common conditions." (PMID 39434928, 2024). "Six months later, blood tests revealed disease recurrence with PTH-dependent hypercalcemia (albumin-corrected calcium 2.74 mmol/L [10.98 mg/dL], PTH 14.5 pmol/L [136.8 pg/mL])." (PMID 39011405, 2024). "pHPT is a common endocrine disorder characterized by the excessive secretion of parathyroid hormone, leading to hypercalcemia, which can manifest with symptoms such as osteoporosis, generalized weakness, and, in severe cases, altered consciousness." (PMID 38201419, 2024). "Using low-calcium dialysate solutions, a lower frequency of hypercalcemia episodes is expected, followed by release of the inhibition in PTH expression and return to the expected—higher than normal range—plasmatic concentrations." (PMID 38785509, 2024). "Our patient had evidence of high normal levels of calcium with significant hypercalcaemia accompanied by raised serum parathyroid hormone levels defining tertiary hyperparathyroidism with a [Ca2+×PO43-] of 141.77 mg2/dl2." (PMID 39295658, 2024). "The concern regarding parathyroid cancer, in this case, was due to the severity of his hypercalcemia, the size of the neck mass, and the extent of his PTH elevation (peak PTH level 17x higher than the upper reference range)." (PMID 39087171, 2024). "Because bisphosphonates are contraindicated in pregnancy, hydration and calcitonin are the cornerstones of treatment for PTH-rp-induced hypercalcemia." (PMID 39148641, 2024). "Upon persistence of hypercalcemia and PTH elevation during the 3-month postoperative follow-up, the patient was referred to our clinic on November 2023." (PMID 39444450, 2024). "Her clinical symptoms were explained by her blood results, which showed PTH-rp-mediated hypercalcemia." (PMID 39148641, 2024). "A 15-year-old girl was referred to our general surgery clinic with postoperative hypercalcemia and elevated PTH levels persisting for 3 months since the thoracoscopic intrathoracic left parathyroidectomy operation for PHPT carried out in another center." (PMID 39444450, 2024). "Our findings of higher odds of mortality is likely more related to non-PTH dependent hypercalcemia of malignancy due to a very low prevalence of hyperparathyroidism in our study population." (PMID 38524024, 2024). "Mutations in this gene raise the set point for calcium homeostasis, meaning higher-than-normal serum calcium levels are required to suppress PTH release, resulting in mild to moderate hypercalcemia with normal to high PTH levels." (PMID 39246902, 2024). "Tertiary hyperparathyroidism is characterized by increased parathyroid hormone (PTH) secretion that appears after prolonged secondary hyperparathyroidism, leading to the onset of hypercalcemia." (PMID 39463573, 2024). "The hypercalcemia was accompanied by a suppressed PTH level, which raised the suspicion of PTH-rp-induced hypercalcemia, which was confirmed by the blood test." (PMID 39148641, 2024).